HIF1A (hypoxia inducible factor 1 subunit alpha)
Diseases named in the same sentence as HIF1A in open-access papers (continued):
Sharing a sentence is not in itself a finding about the gene and the disease.
tumor (continued). "Transcription factors such as HIF-1α and other genes relevant to tumorigenesis are potent PKM2 activators, while a number of genes associated with cell proliferation, metabolism, and tumor growth are downstream targets of PKM2." (PMID 24895527, 2014). "We therefore characterized the nuclear expression profile of HIF1α, HIF2α and HIF3α in the tumor prostate cell lines LNCaP, DU145 and PC3 following oxygen deprivation." (PMID 24801981, 2014). "Having established the specificity of hydroxylated HIF-1α antibodies, we determined the expression in vitro and in vivo in tumour models." (PMID 24563687, 2014). "Although HIF-1α is generally regarded as a tumor-promoting factor in endothelial cells, epithelial cells and myeloid cells, these data indicate that distinct processes can occur depending on the cell type." (PMID 24978438, 2014). "In fact, hypoxia activates tumor promoting stroma cells and HIF-1α has been identified as the major driver of tumor-stroma “co-evolution”." (PMID 24460801, 2014). "Immunohistochemical staining of formalin-fixed, paraffin-embedded tumor tissues demonstrated enhanced intensity of HIF1-α and CA IX staining in the carnosine-treated group." (PMID 24886661, 2014). "Hypoxia also induces hypoxia-stabilized HIF1α (Hypoxia inducible factor-1α) protein that promotes tumor growth, angiogenesis, and metastasis." (PMID 25115393, 2014). "Altogether, these data highlight that parthenolide can affect hypoxic HIF1α activation only in the tumor cells where NF-kB is responsive to oxygen deprivation." (PMID 24801981, 2014). "Progression-free survival was longer for HIF-1α percent of tumor expression groups 0–2 (HIF-1α low) versus 3–4 (HIF-1α high; p = 0.034)." (PMID 25100134, 2014). "To examine the effects of DKKs on tumor hypoxia, we stained tumor sections with hypoxia-inducible factor-1α (HIF-1a), an intrinsic marker of hypoxia." (PMID 24091497, 2014). "There is also EZN-2968, a specific HIF-1α mRNA inhibitor, shown to reduce cancer cell viability and xenograft tumor growth, which is currently under phase I clinical trial." (PMID 24472707, 2014). "Transcription factor HIF-1α plays a crucial role in tumor angiogenesis and regulates the expression level of VEGF." (PMID 25162518, 2014). "Data from both cells lines and tumour xenograft models extends this observation demonstrating conclusively that accumulation of proline-hydroxylated HIF-1α occurs in tumours and cell lines that express wild-type VHL." (PMID 24563687, 2014). "The fact that the expression of HIF-1α increases proportionally to the clinical stage of the tumor is equally important." (PMID 24745019, 2014). "In GBM, gene expression profiles on microdissected cellular zones surrounding necrotic foci have revealed up regulation of HIF-1α, one of hypoxia-inducible factors mediating cancer cell adaptation to a hypoxic tumour environment." (PMID 25279461, 2014). "JMJD1A gene expression is down-regulated by the microRNA mir-155, and up-regulated by hypoxia-inducible factor 1α (HIF1α), hypoxia, starvation and iron scavengers in tumor tissues." (PMID 24742640, 2014). "In patients with G3 lesions, relapse was significantly related to a higher HIF-1α expression in both tumor (P = 0.024) and stromal cells (P = 0.019)." (PMID 25243117, 2014). "Reduced oxygen availability in tumour tissue leads to the activation of a core cellular response to hypoxia, the transcription factors HIF-1α." (PMID 25547490, 2014). "Key examples include the use of liposomal quercetin to eliminate upregulated heat shock proteins and bortezomib to eliminate HIF-1a and thereby increase tumor destruction." (PMID 25133740, 2014).
tumor (continued). "Although a trend can be observed in which lower HIF-1α percent of tumor expression appears to confer longer TTP and OS, these associations were not statistically significant." (PMID 25100134, 2014). "Cellular adaptation to a hypoxic microenvironment is essential for tumor progression and is largely mediated by HIF-1α through coordinated regulation of hypoxia-responsive genes." (PMID 24618817, 2014). "Hypoxia has been shown to induce hypoxia-inducible factor-1alpha (HIF-1α) expression to support many cellular changes required for tumor growth and metastasis." (PMID 25115400, 2014). "Surprisingly, although the Cezanne-regulated degradation of HIF-1α depends on the tumour suppressor pVHL, hydroxylase and proteasome activity are dispensable." (PMID 25355043, 2014). "Collectively, these data suggest that HIF-1β, along with HIF-1α, regulates hypoxic apoptosis of tumor cells under hypoxic conditions." (PMID 25068796, 2014). "HIF-1α represents a key factor in tumor angiogenesis, being able to activate the transcription of VEGF." (PMID 24902850, 2014). "Hypoxia and HIF-1α have been shown to play key role in promoting tumor growth and fueling EMT via various pathways (Notch, hedgehog, Wnt, and TGF-β)." (PMID 24811731, 2014). "Storti and colleagues also showed that selective HIF-1α inhibition reduced tumor burden in vivo and strongly decreased angiogenesis and the development of osteolytic bone lesions." (PMID 24978438, 2014). "Hypoxic tumour cells are more aggressive and metastatic-prone, as they reprogram their metabolism toward aerobic glycolysis through HIF-1α-mediated expression of GLUT proteins and glycolytic enzymes." (PMID 25221641, 2014). "We aimed to validate and use these antibodies for use in immunohistochemistry to gain insights into the hydroxylation status, and therefore mechanism, of HIF-1α stabilisation both in vitro models of hypoxia as well as in tumours in vivo." (PMID 24563687, 2014). "It has been shown that ROS can be produced by the chronic hypoxia of tumor cells, which activate HIF-1α and downstream pathways, enabling tumor cells to acquire invasive competence." (PMID 25174950, 2014). "To this end we optimised antibodies against the proline-hydroxylated forms of HIF-1α for use in formalin fixed paraffin embedded (FFPE) immunohistochemistry to assess effects in tumour cells in vivo." (PMID 24563687, 2014). "The outcome of hypoxia-induced HIF1A activation was shown to be cell context– and tumor microenvironment–dependent." (PMID 25069832, 2014). "Continuous tumor growth is dependent on adaptation of tumor cells to hypoxic stresses and angiogenesis, two processes that are primarily regulated by HIF1A." (PMID 25069832, 2014). "A previous study detected an increase in proline-hydroxylated HIF-1α under hypoxia in vitro, in the tumour cell lines HeLa and HT1080 at Pro564 using similar methodology." (PMID 24563687, 2014). "Cul2 is part of the VHL tumor suppression complex that ubiquitinates HIF1α; the disruption of HIF1α has been found to improve the insulin sensitivity and decrease adiposity in mice." (PMID 24628878, 2014). "HIF1A is a key protein involved in the activation of glycolytic enzymes under hypoxic tumor conditions." (PMID 24879114, 2014). "In contrast to previous data, they observed that ablation of HIF-1α in stromal fibroblasts was able to increase tumor growth and perfusion." (PMID 24978438, 2014). "Functional studies of miR-18a, a relatively understudied MIR17HG family member, revealed a major role in limiting continuous tumor growth and suppressing tumor metastasis, in part by direct regulation of hypoxia-inducible factor 1α (HIF1A) activity." (PMID 25069832, 2014). "Overall, cancer cells trigger oxidative stress in the tumor microenvironment and activate two pro-autophagic promoters, HIF-1α and NFκB, in stromal CAFs." (PMID 25202343, 2014).
tumor (continued). "Normal peripheral mononuclear cells acquire MDSC phenotype following co-incubation with tumor cells via increases in HIF1A expression." (PMID 25294811, 2014). "When a tumor reaches more than 2-3 mm3 in size, a situation of cellular hypoxia occurs favouring expression of HIF-1α." (PMID 26316946, 2014). "HIF-1α and HIF-2α have been reported to promote tumor progression through overlapping functions, however, accumulated evidences indicate that HIF-1α and HIF-2α have their unique roles in cancer cells." (PMID 24505470, 2014). "In our case series, the prognostic relevance of single markers was only observed for tumor and stromal expression of HIF-1α in the G3 subgroupand for stromal HJURP expression in G1-2 lesions." (PMID 25243117, 2014). "HIF-1α and TFE3 staining were located mostly in the nuclear of the AdCC tumor cells as compared with PA (P<0.01 for HIF-1α and P<0.001 for TFE3) and NSG (P<0.01 for HIF-1α and P<0.001 for TFE3)." (PMID 25485635, 2014). "Angiogenesis is crucial to the development of metastasis 35,36, and HIF-1α promotes several important mechanisms to potentiate tumor angiogenesis via various important proangiogenesis events 37, especially upregulation of VEGF expression 38–40." (PMID 24634093, 2014). "The hypoxia responsive element in the CA-ΙΧ gene promoter binds to hypoxia-inducible factor 1α (HIF-1α), and this is expressed in many tumour types, overlapping with vascular endothelial growth factor (VEGF) mRNA and the hypoxia marker pimonidazole." (PMID 25547490, 2014). "Due to its capacity to increase oxygen availability in tissues, as well as to activate anaerobic metabolism, Hif1α plays a fundamental role in tumor growth." (PMID 24465590, 2014). "A dose of 100 μM cobalt chloride (CoCl2), a hypoxia-mimetic agent that induces HIF1α expression, stabilization, and activation, was used to mimic the hypoxia seen during tumor development." (PMID 25310823, 2014). "In tumours, hypoxia stimulates accumulation of HIF-1α by inhibiting proteasomal degradation which in turn stimulates angiogenesis by upregulating the expression of MMP-2 and VEGF." (PMID 25296162, 2014). "HIF-1α knock-down also sensitized tumor cells to IMQ-induced apoptosis, with the rapid depletion of the Mcl-1 protein." (PMID 24658058, 2014). "This was further confirmed by expression of hypoxic marker HIF-1α in the cells (iv) located in tumor regions corresponding to the areas expressing high levels of pSTAT3 (iii)." (PMID 25594014, 2014). "This IMQ-induced HIF-1α expression also occurred in TLR7/8-negative tumor cells, although it has been reported previously that the ligand-induced activation of TLR7/8 leads to the accumulation of HIF-1α protein in THP-1 human myeloid macrophages." (PMID 24658058, 2014). "It has been previously shown that in some neoplasms mTOR is an upstream activator of HIF-1α protein, enhancing its gene transcription." (PMID 25166211, 2014). "Previous studies showed that overexpression of HIF-1α in various tumor types compared to the respective normal tissues, including brain, colon, breast, gastric, lung, skin, ovarian, prostate, and renal carcinomas." (PMID 25548899, 2014). "Overexpression of HIF-1α is common in many malignancies and has been found to be correlated with a poor prognosis of different types of tumor." (PMID 25377659, 2014). "Tumor cells can also increase the expression of HIF-1α by activating AKT under normoxia, and activate downstream target genes under normoxia." (PMID 24662981, 2014). "As expected, the PH domain led to a remarkable decrease in expression of HIF-1α and its target gene expression in tumor tissues." (PMID 25361009, 2014). "Overall, 50% of tumours had detectable HIF-1α (47% head and neck, 57% breast, 45% lung and 38% bladder)." (PMID 24563687, 2014). "Overexpression of HIF-1α is associated with a corresponding large production in VEGF, a growth factor involved in promoting tumor angiogenesis, invasion, and metastasis." (PMID 25140303, 2014).
tumor (continued). "The lowest expression was observed for HIF-1α in both tumor and stromal cells, with a significantly higher expression in tumor cells in G3 with respect to G1-2 lesions." (PMID 25243117, 2014). "P-gp and MRP1 are regarded as energy-dependent membrane efflux pumps and are widely considered to be transcriptionally regulated by HIF-1α in multiple types of human tumor." (PMID 25310259, 2014). "This leads also to an increase in tumor hypoxia by upregulation of hypoxia-inducible factor 1a (HIF1a)." (PMID 25147764, 2014). "The elimination of HIF1-α from the tumor environment provides a potential anti-angiogenic cancer therapy pathway by inhibiting the recruitment of macrophages and other pro-angiogenic cells." (PMID 26932379, 2014). "Hypoxia genes, especially HIF-1α, are frequently upregulated within many solid tumors and promote tumor progression." (PMID 25566498, 2014). "We determined significantly higher levels of HIF-1α protein in tumor compared to normal tissue (p < 0.001)." (PMID 24551593, 2014). "HIF-1α plays an essential role in embryonic vascularization, tumor angiogenesis, and the pathophysiology of ischemic disease." (PMID 25238237, 2014). "For example, lung squamous cell carcinoma patients with high HIF1α expression in tumor cells and low expression in stromal cells had better survival." (PMID 24567056, 2014). "Inhibition of HIF-1α function in tumors has been shown to attenuate or suppress tumor growth in experimental xenograft models." (PMID 25105148, 2014). "Tumor angiogenesis was evaluated by CD34-determined intratumoral MVD in the present study, and high MVD was also associated with high HIF-1α expression and high VEGF expression." (PMID 25162518, 2014). "The von Hippel–Lindau (VHL) tumor-suppressor protein binds specifically to hydroxylated HIF-1α which is then ubiquitylated by E3 ubiquitin-protein ligases and rapidly degraded by the proteasome." (PMID 24886661, 2014). "We also show that rescue of Nrf2 function in fully transformed cells is an effective strategy to tackle in vivo tumor growth, as Nrf2 expression sensitizes transformed cells to apoptosis and impairs the angiogenic response through destabilization of HIF-1α." (PMID 24491031, 2014). "In human oral SCC, a hypoxic microenvironment plays an important role in expressions of HIF-1α and MMPs and in proliferative activity of tumor cells." (PMID 24988190, 2014). "Apart from its role in the development of radioresistance, HIF-1α is crucially involved in tumor angiogenesis, invasion, survival, and growth." (PMID 24717239, 2014). "In contrast, in the analysis of HIF-1α percent of tumor expression, PFS was statistically significantly different between groups 0–2 (i.e., 0–50 % or low expression) versus groups 3–4 (i.e., 51–100 % or high expression) (p = 0.0341)." (PMID 25100134, 2014). "When a tumor develops regions of inadequate oxygen supply, HIF1-α subunits are stabilized, recruiting bone marrow (BM)-derived cells including macrophages that up regulate angiogenesis." (PMID 26932379, 2014). "CoCl2 is a chelating agent that traps iron ions and acts to inhibit cellular uptake of oxygen and increased HIF-1α expression in tumor cells." (PMID 25140303, 2014). "HIF-1α overexpression has been identified in a number of tumor types, including pancreatic, head and neck, breast, renal, ovarian, bladder, brain, colorectal, and prostate cancers, and overexpression correlates with increased angiogenesis and metastasis." (PMID 25373733, 2014). "In fact, its oncogenic effect is related to the complex NGAL/MMP-9; while its anti-tumor effect is related to the inhibition of the pro-neoplastic factor HIF-1a, the HIF-1a-dependent VEGF and FAK." (PMID 24742531, 2014). "In cell lines exposed to hypoxia we observe heterogeneity in the accumulation of proline-hydroxylated HIF-1α, suggesting that tumour cells have major differences in their degradation pathways." (PMID 24563687, 2014).
tumor (continued). "Of note, consistent with the previous findings, silencing of HIF-1α also displayed suppression of tumor cell growth under hypoxic conditions, which is probably mediated by inhibition of several other targets related to cell proliferation." (PMID 25068796, 2014). "Overexpression of HIF-1α, an oxygen-dependent α subunit of HIF, has been associated with tumor cell growth, lymph node metastasis and survival in head and neck tumors." (PMID 24988190, 2014). "Hypoxia-inducible factor 1α (HIF-1α), a major mediator of tumor physiology, is activated during tumor progression, and its abundance is correlated with therapeutic resistance in a broad range of solid tumors." (PMID 25420025, 2014). "Cellular proliferation at an enhanced rate at tumor sites gives rise to hypoxia, low concentration of oxygen that stabilizes HIF-1α, which activates NFκB to secrete an angiogenic protein, VEGF and also induces expression of IL-12 and TNF-α." (PMID 24782866, 2014). "Here we show that upregulation of SHARP1 suppressed tumor angiogenesis by decreasing hypoxia-inducible factor-1α (HIF-1α), inhibited cell viability and tumor growth in EC." (PMID 24918449, 2014). "Using Cx43 shRNA stable transfectants whose Cx43 expression was reduced, we demonstrate that abrogation of Cx43 expression resulted in increased HIF-1α expression and transcriptional activity in tumor cells." (PMID 25548899, 2014). "HIF-1α down-regulation significantly inhibited neo-angiogenesis both in BM as well as in other tumor masses." (PMID 24711541, 2014). "Overexpression of SHARP1 in vivo inhibited tumor growth and angiogenesis, and decreased HIF-1α expression." (PMID 24918449, 2014). "This work represents the first link between the functional ablation of Rb in tumor cells and HIF1α-dependent invasion." (PMID 24919196, 2014). "Tumor oxygen condition and gene variation have been found to synergistically regulate the expression levels and activity of HIF-1α." (PMID 25013467, 2014). "On the contrary, hypoxic apoptosis was markedly increased by silencing HIF-1β, a finding similar to the effect of HIF-1α-silencing on tumor cell survival." (PMID 25068796, 2014). "In contrast, HIF-1α knockdown using shRNA significantly decreased growth in hypoxia, and reduced by more than 50% tumor invasion in four lines with high HIF-1α baseline levels." (PMID 25166211, 2014). "In fact, HIF-1α over-expression is a common feature of human cancers, where it mediates the adaptation to the hypoxic tumour microenvironment." (PMID 24804733, 2014). "It has been proposed that vascular endothelial growth factor (VEGF) and hypoxia-inducible factor-1α (HIF-1α) play critical roles in tumor angiogenesis." (PMID 25162518, 2014). "HIF1α also induces genes that promote angiogenesis, anaerobic metabolism, survival pathways while down-regulating tumor suppressive miR expression." (PMID 25115393, 2014). "UT-SCC-5 hSCC was chosen for the experiments because this tumor model is more radioresistant and exhibits higher expression of HIF-1α and hypoxic fraction as compared with UT-SCC-14." (PMID 25234922, 2014). "The same rational is true regarding the glucose uptake ability, since mTOR increases GLUT1 expression via HIF1α in some tumours, while AMPK pathway also leads to increased glucose uptake and hexokinase activity in normal thyrocytes." (PMID 27919039, 2014). "Immunohistochemical staining showed that the expression of SHARP1 was negatively correlated with tumor stage, histological grade, myometrial invasion, lymph node metastasis, blood vessel permeation in the myometrium and HIF-1α expression." (PMID 24918449, 2014). "HIF-1α is a transcription factor that permits the adaptation of tumor cells to changing environment, such as hypoxia." (PMID 24629239, 2014). "Inhibiting HIF-1α function in the tumor microenvironment is important for suppressing tumor angiogenesis and increasing tumor cell apoptosis." (PMID 24465898, 2014).